CD69 (CD69 molecule)
Diseases named in the same sentence as CD69 in open-access papers (continued):
Sharing a sentence is not in itself a finding about the gene and the disease.
tumor (continued). "Furthermore, the T-cell activation proteins CD39, CD69, and PD-1 showed higher expression in the tumor compared to the blood." (PMID 39918475, 2025). "We did not assess antigen specificity; hence, it is unclear whether CD69− and CD69+ T cells are directed against tumor-specific antigens." (PMID 40361474, 2025). "Flow cytometric analysis of tumor-infiltrating leukocytes revealed that tumors injected with IFNβ-mRNA LNPs were associated with an increased CD8:CD4 T-cell ratio among lymphocytes, more CD69-expressing CD8 T-cells, and an increased presence of M1 macrophages." (PMID 40006725, 2025). "Regarding NK cells, significantly positive correlations were obvious for NKp46+ NK cells and CD69+ NK cells in PB or ascites samples in association with corresponding tumor tissues, irrespective of CD16 expression." (PMID 41221283, 2025). "Its upregulation in tumor‐specific CD8+TRM cells promotes the expression of other important TFs, including Blimp1 and its homologue Hobit, and residency‐associated molecules, such as CD103 and CD69." (PMID 40066223, 2025). "Similarly, CAR T cells from GPR65 KO tumors showed elevated expression of activation markers CD25 and CD69, consistent with the increased tumor burden and antigen exposure." (PMID 39998425, 2025). "Notably, 22.0405.aF increased both the frequency and functional activation of CD56+ NK cells within the tumor microenvironment, as reflected by elevated CD69 expression and a fivefold increase in intracellular IFN-γ production." (PMID 41479906, 2025). "In the Oncology VascHT29 Combo ELECT system, Keytruda (50,000 ng/mL) also reversed the hsa/mtCXCL8-mediated inhibition of key adhesion molecules like VCAM-1, CXCL-10, CXCL-9, and CD69 at the highest dose, promoting immune cell adhesion and recruitment into the tumor site." (PMID 40124384, 2025). "In addition, to further identify the tumor killing efficiency of the CD69+CD8+ T cells, the Panc02‐based subcutaneous tumor model was reconstructed and treated with PBS, αMSLN, PancNV and the combined (αMSLN plus PancNV) therapy, respectively." (PMID 39887656, 2025). "CD69 expression, an indicator of recent activation, was observed in shared T cell clonotypes in both patients; however, it was only significantly elevated in the tumor specimen of su001, who achieved remission." (PMID 40314973, 2025). "Finally, the FGF/FGFR1/NOTCH1 within RB1 variant group has a remarkably high ratio of inner‐tumor CD8+ T cell infiltration, non‐exhausted T cells, exhausted TCD8+PD‐1+LAG3− cells, and TRMCD8+CD69+CD103+cells." (PMID 40001320, 2025). "Additionally, the density of tissue-resident CD8+ tumor-infiltrating lymphocytes (TILs) expressing CD69+CD103+ was noticeably higher in the tumor edge zone and tumor core zone than in the stromal zone." (PMID 40070825, 2025). "A higher tumor grade positively correlated with CD69+CD103+CD4+ T cells in the tumor." (PMID 40361474, 2025). "Moreover, significantly high proportions of tumor-infiltrated CD69+ γδT cells and PD-L1+ γδT cells were detected being at least 3-times more abundant than ascites-derived γδT cell counterparts." (PMID 41221283, 2025). "Furthermore, genes associated with proliferation and survival, including CD69, EGR1 (early growth response protein 1), and PIM2 (proviral integrations of moloney virus 2), were increased, suggesting a potential role in tumor progression." (PMID 40809351, 2025). "In patient blood and tumor, CD69-expressing iNKT cells displayed a higher global metabolism than non-expressing cells, which was associated with a longer PFS in blood, but shorter PFS for tumor." (PMID 41562072, 2025). "CD69+ T cells were associated with immune exhaustion and tumor aggressiveness, whereas CD69− T cells appeared to significantly contribute to the influence of alcohol intake on the immune landscape of HCC in the tumor microenvironment." (PMID 40361474, 2025).
tumor (continued). "Impaired T cell activation was detected when T cells were incubated with macrophages that cocultured with DNA hypermethylated NPC cells induced by C1q, as indicated by a decline in CD69 expression, while comparable CD69 levels in T cells were observed when tumor cells were treated with Azacitidine." (PMID 40171991, 2025). "Consistently, we detected significantly increased infiltration and activation of CD8+ T cells in the shTrp63 group compared with the Scramble group in HNM007 tumor samples, as measured by the levels of activation and cytotoxic protein markers (CD69, GZMB, IFNγ) using flow cytometry analysis." (PMID 38509096, 2024). "In addition, homing and activation-related proteins L-selectin (CD62L), CD5 and CD69 in T cells were down-regulated to varying degrees in G-MDSCs group, which suppressed the antitumor immune activity of tumor-infiltrating T cells." (PMID 38169579, 2024). "Furthermore, out of all T cells within the TIME, CD4+ TCMs, CD4+ TEMs and CD8+ TEMs are the most activated/exhausted subsets, indicated by the increased expression of CD69 and PD1, which is associated with hampered anti-tumor response." (PMID 39044825, 2024). "Additionally, CD69 was expressed on 34.2% (± 11.26) of hYP218 CAR T cells in tumour tissue and 44.2% (± 5.52) in the spleen." (PMID 39548594, 2024). "Furthermore, the activation level of tumor‐infiltrated T cells, evaluated by the CD69 expression level, was decreased in mice with anti‐CD4 treatment in comparison with IgG treatment." (PMID 39225354, 2024). "Interestingly, in mice, CD69 was identified as a relevant factor for the exhaustion of tumor-infiltrating lymphocytes (TILs)." (PMID 38515578, 2024). "In addition, the frequencies of tumor necrosis factor (TNF)‐α+interferon (IFN)‐γ+, CD62L‐CD44+, and CD69+ tumor‐infiltrating CD8+ T cells were increased by anti‐PD‐1 mAb in tumors with APOC2‐K70R." (PMID 38981044, 2024). "Considering previous studies demonstrating HIF-1α can directly regulate expression of T cell activation-related genes such as CD69 in tumor-infiltrating lymphocytes, it would be informative to examine how PX-478 impacts levels of canonical activation markers on mesoCAR T cells." (PMID 38425341, 2024). "Finally, we also examined the levels of CD69 expression on T cells isolated from tumor bearing mice." (PMID 38498459, 2024). "Furthermore, significant increases in CD69 expression levels in the treated tumor and PD-1 expression levels in both tumors on CD8+ T cells were detected, indicating activation." (PMID 39410025, 2024). "CD69 on NK cells appears to play a crucial role in initiating tumor cell lysis, therefore its reduced expression may impair the anti-tumor response." (PMID 39004641, 2024). "In addition to the in vitro coculture system, we also observed increased CD69 expression on T cells in the B16-OVA syngeneic tumor model following VC treatment." (PMID 39388288, 2024). "The poised Teff cells may migrate locally toward the tumor, or re-circulation may also be possible, as seen in CD69+ intrahepatic γδ T cells, though we are unable to report evidence for this in our data as we focus only on the colon." (PMID 39454432, 2024). "Interestingly, CD69, an early T cell activation marker and tumor-infiltrating T cell exhaustion marker, was partially detected in the neoantigen-specific T cells." (PMID 38349410, 2024). "Additionally, most of the T cells detected in untreated tumors stained positive for CD69, suggesting they were “activated” despite the substantial tumor size." (PMID 38201300, 2024). "In addition, we further validated the expression patterns observed in our transcriptomic analysis, identifying increased expression of LAG-3 and CD69 as characteristic features of the CD49a+ ‘tumor -retained’ state." (PMID 38267402, 2024). "A smaller population of CD69+CD103+ CD4+ T cells was also apparent within the tumor." (PMID 36689623, 2023).
tumor (continued). "CD69 is a glycoprotein type II known to regulate inflammation through T-cell migration and retention in tissues and has a crucial role in inducing the exhaustion of tumour-infiltrating T cells." (PMID 37875584, 2023). "Finally, the presence of CD69+ HSC-like cells is associated with unfavorable genetic mutations, the persistence of residual tumor cells in chemotherapy, and poor outcomes in independent pediatric and adult public AML cohorts." (PMID 37653425, 2023). "Further studies are certainly warranted to interrogate this theory and elucidate whether CD69 may be a viable novel target for cancer immunotherapy in OGJ in combination with FLOT or CROSS regimens to prevent tumour immune escape mediated by T cell exhaustion." (PMID 35986757, 2023). "A strong correlation between the percentage of activated splenic cytotoxic T lymphocytes (CD8 + CD69 +) of all live cells in the spleen and the tumor size was observed, indicating that this could be a potential measure for therapy response in this model." (PMID 37118819, 2023). "Subsequently, continuous tumor antigen stimulations lead to the exhaustion of CD69 positive TILs." (PMID 37180581, 2023). "Finally, the authors revealed that activated CD8+CD69+ lymphocyte infiltration into the spleens correlated inversely with the tumour weight." (PMID 37887559, 2023). "All these studies imply that CD69 play a negatively regulated role in anti-tumor immune responses." (PMID 37180581, 2023). "Importantly, CD69+CD103+ tumor‐resident CD8+ T cells and local IL‐15 production were associated with response to immune checkpoint inhibitors." (PMID 37144705, 2023). "In addition, the proportion of CD69+ CD8+ T cells was greatly increased in tumours with TRIM21 depletion." (PMID 36797289, 2023). "Moreover, nodal metastasis tended to be associated with low levels of CD69, MYD88, and TLR4 mRNA expression within the tumor (p = 0.11, p = 0.06, and p = 0.06, respectively)." (PMID 36281585, 2023). "Overall, these studies suggest a key role of CD69 in T-cell exhaustion through the regulation of PD-1 expression, conceivably by the activation of CD69-mediated signaling by known or unknown ligands in the tumor microenvironment." (PMID 37223078, 2023). "A possible explaination is that PD-1 mAb may trigger the interaction between CD69 molecule expressed on TILs and unknown ligands on tumor cells." (PMID 37180581, 2023). "Additionally, anti-CD69 monoclonal antibody treatment attenuated the T-cell exhaustion and tumour progression in tumour-bearing mice." (PMID 35986757, 2023). "In line, in vivo inhibition of IgA signaling decreased the number of tumor-infiltrating IgA+PD-L1high macrophages and increased the infiltration of CD69+CD8+ T cells, eventually leading to anti-tumoral effects in a Cell-Derived tumor Xenograft (CDX, Hepa 1-6 cells) model." (PMID 36845555, 2023). "have shown that tumor growth and metastasis were attenuated in Cd69-/- mice." (PMID 37655095, 2023). "In addition, the proportions of activated CD8+CD69+ T cells were clearly increased in the tumor tissues, blood, and spleen of GPR84−/− mice." (PMID 37105980, 2023). "Although we observed no impact of VSVΔ51+T-DM1 on the activation status of CD8+ T-cells in tumours, TdLN, or spleens, our analyses revealed an average 2-fold increase in activated CD44hi, CD25+, or CD69+ tumour-infiltrating CD4+ T-cells in the same treatment group, relative to PBS or monotherapies." (PMID 37153626, 2023). "Notably, UTMD‐mediated BMP9 delivery increased the expression of the activation marker CD69 in NK cells, restoring the anti‐tumour function of NK cells when administered in combination with the PD‐L1 inhibitor." (PMID 37132170, 2023). "Moreover, the early activation marker CD69 signals that these T-cell subpopulations swiftly responded upon encountering MAGE-A4-expressing tumor cells." (PMID 37894816, 2023).
tumor (continued). "In most cases, T-cells (both CD4+ and CD8+) in the tumor microenvironment display an activated phenotype represented by an increased expression of activation markers (i.e., CD69, CD25, CD95, CD44, and HLA-DR) and concomitant decrease in naive T-cells markers (CD45RA and CCR7)." (PMID 37835465, 2023). "At 6 days post-tumor cell injection, analysis of the draining medLNs revealed a 1.8-fold increase in the frequency of CD44+CD69+CD8+ T cells, a phenotype associated with early T cell activation, in B16F10-OVA tumor-bearing B6 mice (B16) compared to uninjected B6 mice." (PMID 37426658, 2023). "However, CD4+ and CD8+ CD69+CD103+ sTRM cells expanded with FTY720 treatment compared with 0 day group before the tumor rechallenge." (PMID 37407600, 2023). "We then determined whether the increased proportions of CD8+ CD69+ CD44hi and CD4+ CD69+ CD44hi T cells following ex vivo restimulation with viable 4T1 tumor cells would correspond with increased IFN-γ production." (PMID 36839766, 2023). "Next, we evaluated whether NaHCO3 enhanced anti-PD-L1-induced T cell activation in vivo by analyzing the frequencies of CD69+ T cells in the collected tumor tissues, TDLNs and spleens." (PMID 37894298, 2023). "In addition, we performed IHC staining to evaluate the expression of CD69 on TILs from GL261 tumor–bearing mice in control and ICI-treated animals." (PMID 37426447, 2023). "In vivo, preloading with unlabeled CD69 Ab administered 24 hours prior to tracer injection significantly reduced tracer uptake in the immune periphery (i.e., spleen) while enhanced tumor-specific 89Zr-DFO-CD69 Ab uptake, as indicated by the SUV values and BioD data." (PMID 37426447, 2023). "The CD69+CD103+ subgroup showed enhanced anti-tumor function in mediating tumor lysis." (PMID 37240834, 2023). "In the melanoma tumor microenvironment, abundant CD69+ T cells are found." (PMID 37144705, 2023). "Interestingly, there was a positive correlation between CD44+ and CD69+ expression on CD8+ PD-1− TILs on both sides of tumor." (PMID 36513720, 2022). "Although CD69 was more highly expressed on PD-1+ cells, nearly half of PD-1- cells also expressed CD69, indicating that a portion of these cells are also resident in the tumor." (PMID 35584630, 2022). "Interestingly, late-stage tumor induced enhanced CD69+CD103+ stem-like Pmel-1 T cell differentiation in TDLNs." (PMID 36229613, 2022). "Moreover, the TbsAb.short form mediated better T cell-tumor cell aggregation and increased CD69 and CD25 expression levels on T cells more than the TbsAb.long form." (PMID 36291540, 2022). "However, the proportion of NK cells expressing CD94 and the activation/exhaustion marker CD69 significantly increased in higher tumor stages compared with stage I and the healthy controls." (PMID 36428793, 2022). "This analysis showed that CD69 is aberrantly expressed in most TCGA tumors, and that its expression positively correlated with most immune checkpoints and immune cell infiltration of the tumor microenvironment." (PMID 36045683, 2022). "The increased frequencies of CD69+ lymphocytes in the tumor microenvironment may be the result of exposure of lymphocytes with tumor antigens." (PMID 35158748, 2022). "As expected for mucosal tumor, we could detect a significant number of CD69+CD103+ TRM-like cells in bulk CD8+ TEMs isolated from the tumors." (PMID 36229613, 2022). "The combination therapy also enhanced the high infiltration of effector CD44+ and CD69+ CD8+ PD-1− on both sides of tumor, which may have a role in the antitumor response." (PMID 36513720, 2022). "Subsequent results showed that transfer of miR-92b via TDEs could significantly inhibit CD69 expression on NK-92 cells and reduced their cytotoxicity against parental Hep3B tumor cells." (PMID 35031075, 2022). "CD69 can act as a CD8+ tumor-infiltrating lymphocyte (TIL) activation marker." (PMID 36358600, 2022). "In addition, we also recorded a 3.79 times higher level of CD19+ CD69+ B cells in the tumor samples." (PMID 35158748, 2022).
tumor (continued). "To evaluate the tumor-killing activity of TCRαβ+CD8αα+ IELs, we detected the levels of PD-1, an inhibitory receptor of T cell cytotoxicity, and CD69, an activation marker of T cells, and found they remained similar levels between TCRαβ+CD8αα+ IELs from Kdm6bF/F and Kdm6bF/F-CD4Cre mice." (PMID 34999729, 2022). "Finally, the frequency of CD69+ NK cells was increased in the lymph nodes from CT26 tumor-bearing animals, corresponding to the NK-cell activation observed in vitro." (PMID 36923556, 2022). "While the coculture with m-reMAIT cells did not markedly upregulate the expression of CD69 (CD69+ cells) in NK cells, the addition of Yac-1, an NK cell-sensitive tumor cell line (alone or in combination with m-reMAIT cells), increased the percentage of CD69+ cells." (PMID 35379387, 2022). "Through co-culture experiments with immune cells, we demonstrated the increase of (i) CD86 maturation marker on dendritic cells, (ii) CD69 activation marker on cytotoxic T cells, and (iii) phagocytosis of tumor cells following treatment with SIX2G, confirming the onset of an immunogenic cascade." (PMID 36142133, 2022). "CD4+CD69+FOXP3− Tregs accounted for the vast majority of tumor‐infiltrating Tregs compared with FOXP3+ Tregs and could suppress the CD4+ T‐cell response mainly through mTGF‐β1." (PMID 35474948, 2022). "All constructs were transduced into TCR-deficient Jurkat76 (J76) cells, yielding similar γδTCR surface expression levels, and CD69 upregulation by J76 cells upon co-culture with the tumor cell line Daudi, was used as a marker for TCR-mediated T-cell activation." (PMID 35874769, 2022). "These novel CD4+CD69+FOXP3− Tregs accounted for the vast majority of tumor‐infiltrating Tregs compared with FOXP3+ Tregs and could suppress the CD4+ T‐cell response mainly through mTGF‐β1,145, 146 which was correlated with tumor progression." (PMID 35474948, 2022). "Conceivably, the regulatory role of CD69 in tumour and inflammatory responses could be mediated, at least in part, by modulation of PD-1 expression." (PMID 35930205, 2022). "Finally, evaluation of endogenous tumor immune infiltrate revealed a significantly higher frequency of activated (CD69+ Ki67+) NK cells and fewer M2 (F4/80+ CD206+) macrophages upon 4G- versus 2G-CAR-T cell transfer." (PMID 33156338, 2021). "In addition, PD-1 Ab treatment has been shown to lead to the expansion of a CD8 T-cell cluster in the tumor, expressing Tbet+Eomes+MHCII+BATF+PD-1+TIM-3+CD27+CD69+Gata-3+ that correlated with small tumor size." (PMID 34912335, 2021). "Interestingly, CD8+/CD69+ cells showed an obvious reduction in tumor tissue at day 14 compared with day 7 in both groups (p < 0.001)." (PMID 34950581, 2021). "The overexpressed miR-92b in HCC-derived exosomes actively infiltrates NK cells in the tumor microenvironment, participating in the inhibition of CD69 expression and antagonizing the cytotoxic effects of NK cells on HCC, thereby inducing immune escape of tumor cells." (PMID 33869059, 2021). "Moreover, CD69+CD103+CD8+ T cells from anti-PD-1-treated B16F10E-KO tumours expressed more frequently granzyme B than isotype-treated B16F10E-KO." (PMID 34471106, 2021). "Hence, we also analyzed the activated CD8+ T cells (CD8+/CD69+ cells) in both spleen and tumor tissue by FACS." (PMID 34950581, 2021). "CD103 and CD69 were highly co‐expressed in hILC3s, a characteristic of tissue‐resident innate memory cells, and non‐recirculating immune cells that reside in tumor sites." (PMID 34496133, 2021). "However, IL-10 was expressed by significantly more tumor-infiltrating CD8+CD103+ TRMs than CD69− T cells (p=0.0239, n=10 tumors) and CD103− TRMs (p=0.0423)." (PMID 33479027, 2021). "Moreover, an increase in the CD69 and IFNγ markers in the splenic NK cell population, a feature similar to that in tumor infiltrating immune populations was observed." (PMID 34696515, 2021).